IL36RN (interleukin 36 receptor antagonist)
Diseases named in the same sentence as IL36RN in open-access papers (continued):
Sharing a sentence is not in itself a finding about the gene and the disease.
pustular psoriasis (28 papers, 2015 to 2025). "IL36RN gene mutations are a well-known cause of pustular psoriasis by increasing IL-6 production and offer a chance for target therapy of the skin disease." (PMID 39873967, 2025). "Preliminary research suggests that patients with ACH are more likely than patients with other forms of pustular psoriasis to carry two distinct mutations (ie, IL36RN and AP1S3 or IL36RN and CARD14)." (PMID 40895565, 2025). "Another genetic defect associated with pustular psoriasis is the IL36RN mutation, which decreases activity of the IL-36R antagonist and increases IL-36R signaling, leading to expression of IL-1β and CXCL8." (PMID 38448036, 2024). "On the other hand, the presence of IL36RN disease alleles demonstrated a dose-dependent influence on the age of onset across all types of pustular psoriasis." (PMID 37372477, 2023). "The prevalence of IL36RN mutations among pustular psoriasis subtypes is different; patients with GPP have the highest prevalence of these mutations (23.7%)." (PMID 37372477, 2023). "Another study investigating genetic variations in patients with pustular psoriasis found that AP1S3 mutations were in fewer GPP cases than IL36RN, and patients with AP1S3 disease alleles were mainly female." (PMID 37372477, 2023). "Homozygous mutations in the IL-36RN gene are associated with earlier age of onset in all variants of pustular psoriasis, more severe disease evolution, and different therapeutic responses when compared to plaque psoriasis." (PMID 34838431, 2022). "The analysis of 5,249 patients with different forms of pustular psoriasis showed that IL36RN mutations are the most frequently observed genetic abnormality in pustular psoriasis." (PMID 34838431, 2022). "In a study on 57 Chinese patients with pustular psoriasis, IL36RN mutations were found in 75% of GPP patients and 94% of ACH patients." (PMID 33919434, 2021). "Mutations in IL36RN, which were first described in 2009 in two families with severe pustular psoriasis, lead to functional impairment of IL-36Ra and subsequent amplification of the downstream inflammatory responses." (PMID 34445754, 2021). "Our study showed that IL36RN mutations are the most frequent genetic abnormality observed in pustular psoriasis." (PMID 30036598, 2019). "We also found that IL36RN mutations are associated with an earlier age of onset across all variants of pustular psoriasis." (PMID 30036598, 2019). "IL-36RN is a gene encoding the native inhibitor for IL-36, and is deficient in severe pustular psoriasis." (PMID 30356900, 2018). "Taken together, these observations validate the involvement of AP1S3 in pustular psoriasis and suggest the possibility of epistasis between IL36RN and AP1S3 alleles." (PMID 27388993, 2016). "The interleukin-36 receptor antagonist (IL-36Ra) which regulates IL-36α, -β and -γ is linked to psoriatic inflammation, especially loss-of-function mutations in pustular psoriasis subtypes." (PMID 27101808, 2016). "IL36-RN mutations show significant differences among subtypes of pustular psoriasis." (PMID 40176872, 2025). "For instance, the interaction between DCUN1D3 and IL36RN, a key antagonist of IL - 36 receptor signaling, implies a role in modulating IL - 36 dependent epidermal barrier dysfunction, a mechanism recently implicated in pustular psoriasis." (PMID 40959079, 2025). "The main genes implicated in pustular psoriasis are IL36RN, CARD14, and AP1S3." (PMID 38785955, 2024). "Hence, in order to ascertain if IL36RN alleles are the crucial determinants of pustular psoriasis across various disease subtypes, a regression analysis was carried out, incorporating clinical diagnosis as a covariate." (PMID 37372477, 2023). "IL36RN mutations are the genetic variant most frequently observed in patients with pustular psoriasis (5–24%), followed by AP1S3 in 7–11% and CARD14 in a very small number of subjects; the highest rates correspond to patients with GPP, and the lowest correspond to PPP in all cases." (PMID 33919434, 2021).
pustular psoriasis (continued). "Pustular psoriasis’, an uncommon variant, pathogenesis involves a mutation in IL-36RN." (PMID 34884596, 2021). "Thus IL36RN alleles have shared genetic effects across pustular psoriasis subtypes but occur at a very low frequency among patients with PPP." (PMID 30036598, 2019). "Importantly, IL36RN disease alleles had a dose-dependent effect on age of onset in all forms of pustular psoriasis (P = .003)." (PMID 30036598, 2019). "We next sought to determine whether IL36RN alleles were associated with key features of pustular psoriasis across disease subtypes." (PMID 30036598, 2019). "The underlying disease mechanism of AGEP currently remains unknown but recent identification of IL36RN mutations being a causative factor in patients suggests a genetic and mechanistic connection between pustular psoriasis and AGEP." (PMID 30386326, 2018). "In pustular psoriasis, mutations in the IL36RN gene, encoding IL-36Ra, result in its dysfunction, exacerbating downstream inflammatory cascades." (PMID 40563457, 2025). "Mutations in IL-36RN can lead to DITRA, which is correlated with a severe course of pustular psoriasis." (PMID 31736959, 2019). "Similarly, a number of variants have allele frequencies less than global populations like rs148755083 in IL36RN for pustular psoriasis." (PMID 34905135, 2021). "Thus far, genetic studies have only investigated IL36RN gene of this family in relation to pustular psoriasis." (PMID 30634937, 2019). "Therefore, IL-36RN-associated GPP, and CARD14-mediated pustular psoriasis, PRP type V and familial keratosis lichenoides chronica (KLC) caused by NLRP1 mutation, can be considered AIKDs." (PMID 30386326, 2018). "Patients with GPP carrying loss-of-function (LoF) mutations in IL36RN (encoding IL-36 receptor antagonist) or heterozygous mutations in AP1S3 (resulting in increased IL-36α expression) were described, suggesting a pivotal role of IL-36 cytokine activity in driving pustular psoriasis." (PMID 30386326, 2018). "In 2014, mutations in AP1S3, the gene encoding AP-1 complex subunit sigma 3, were found in unrelated individuals with severe pustular psoriasis, including patients with GPP not harboring IL36RN and CARD14 mutations." (PMID 34445754, 2021).
psoriasis vulgaris (13 papers, 2017 to 2025). Plaque psoriasis is the most common presentation of psoriasis. "The most recent analysis, which included a cohort of 251 unrelated patients with GPP from multiple countries, also showed that IL36RN gene mutations were associated with an early age of onset, prevalence of psoriasis vulgaris, and high recurrence rate of GPP." (PMID 34445754, 2021). "Another hypothesis indicated that heterozygous or compound heterozygous mutations of IL36RN may be a predisposing factor for GPP with psoriasis vulgaris because three of 20 GPP patients with psoriasis vulgaris complications were found to carry heterozygous IL36RN variants." (PMID 31789248, 2019). "Overall, the prevalence of IL36RN mutations in patients with GPP has ranged between 10% and 82%, and was significantly lower in cases with associated plaque psoriasis than in those linked to GPP alone." (PMID 34445754, 2021). "They showed that all GPP patients without psoriasis vulgaris carried homozygous or compound heterozygous mutations in the IL36RN gene, whereas only 2 out of 20 cases of GPP with psoriasis vulgaris harbored compound heterozygous mutations." (PMID 34445754, 2021). "In fact, most IL36RN mutations are identified in patients with GPP that do not suffer from concurrent plaque psoriasis." (PMID 34445754, 2021). "Furthermore, both the CARD14 pathway and the IL36RN pathway are associated not only with GPP, but also with psoriasis vulgaris." (PMID 32153585, 2020). "Interestingly, though abnormalities in IL-36 signaling and IL-36g/a genetic polymorphisms are implicated in plaque psoriasis pathogenesis, IL36RN is not." (PMID 38785955, 2024). "IL36RN mutations do not contribute to the risk of plaque psoriasis." (PMID 34445754, 2021). "IL-36Ra (IL-1F9), an anti-inflammatory natural IL36R antagonist, is encoded by the IL36RN gene and is abundantly present in the skin of patients with psoriasis vulgaris, which may constitute part of the “checks and balances” that control the psoriatic inflammation." (PMID 31402919, 2019). "This significant observation allowed the use of biologics, known for being effective in the treatment of plaque psoriasis, to be also used in GPP, regardless of IL36RN mutation status." (PMID 34445754, 2021).
palmoplantar pustulosis (6 papers, 2018 to 2025). A rare skin disease characterized by chronic eruption of sterile pustules on an erythematous and desquamative background, affecting the palms and soles, sometimes also the lateral aspects of hands and feet. "The aim of this study was to evaluate the mutation of IL36RN in Chinese patients with palmoplantar pustulosis." (PMID 31789248, 2019). "Palmoplantar pustulosis is associated with missense mutations in CARD14, but not IL36RN." (PMID 29963046, 2018).
Arthritis (3 papers, 2006 to 2025). Inflammation of a joint. "In cases with EN and arthritis, pathogenic variants of CLUH and IL36RN genes were detected." (PMID 39992598, 2025).
asthma (3 papers, 2023 to 2025). "The Venn diagram showed that there are indeed common DEGs between obesity and asthma, namely IL36RN, PHACTR3, SLAMF7, AKR1B10 and RNF182." (PMID 37723557, 2023).
atopic dermatitis (3 papers, 2017 to 2021). "The reported list of inflammatory mediators found in atopic dermatitis includes S100A7, S100A8 S100A9, CCL2, CCL3, IL36A, IL36G, and IL36RN." (PMID 34925353, 2021).
inflammatory skin disease (3 papers, 2010 to 2018). Inflammatory skin disorders covers a broad category that includes many conditions ranging in severity, from mild itching to grave medical health complications These disorders are common in people of all ages and races. "IL36RN is quite recently identified to have substantial role in different inflammatory skin diseases." (PMID 27774448, 2016).
skin inflammation (3 papers, 2021 to 2024). "Dysfunction of the IL‐36 receptor antagonist (IL‐36Ra), encoded by IL36RN, initiates a downstream inflammatory cascade, while activation of CARD14, encoded by CARD14, promotes skin inflammation by activating NF‐κB in epidermal keratinocytes." (PMID 39373130, 2024).
contact dermatitis (2 papers, 2020 to 2022). An inflammatory skin condition caused by direct contact between the skin and either an irritating substance or an allergen. "We examined whether a loss-of-function IL36RN mutation exacerbates contact dermatitis and evaluated the changes in contact dermatitis-related cytokines." (PMID 31959814, 2020). "However, it has never been determined whether interleukin-36 receptor antagonist (IL-36Ra) deficiency is an exacerbating factor in contact dermatitis." (PMID 31959814, 2020). "The wild-type mice showed an increase in neutrophil infiltration more than the Il36rn−/− mice, indicating that, acquired immunity plays a central role in the CHS response, but we speculated that the innate immune system plays a key role in enhancing the contact dermatitis response in Il36rn−/− mice." (PMID 31959814, 2020).
periodontitis (2 papers, 2019 to 2021). An acute or chronic inflammatory process that affects the tissues that surround and support the teeth. "The role of IL‐36 receptor antagonist (IL36RN), a mutated gene expression of IL‐36 in periodontitis patients with peripheral blood mononuclear cells (PBMC) and plasma remains to be undetermined." (PMID 34272761, 2021). "Furthermore, in the current study significance of IL36RN mutated gene was significantly distinguishing mild vs severe periodontitis and moderate vs severe periodontitis of PBMC and plasma samples with a potential AUC range of 0.73 to 0.85." (PMID 34272761, 2021). "Taken together, IL36RN mutation may not only affects the pathogenesis of periodontitis but also may accurately differentiate mild‐to‐severe and moderate‐to‐severe periodontitis." (PMID 34272761, 2021). "However, the role of IL‐36RN, a mutated gene expression of IL‐36 in periodontitis patients with peripheral blood mononuclear cells (PBMC) and plasma remains unknown." (PMID 34272761, 2021). "Further, a positive correlation of IL36RN expression was significantly observed between PBMC and plasma of periodontitis patients while IL36RN expression was negatively correlated to serum‐based three different cytokines of periodontitis patients." (PMID 34272761, 2021). "These heatmap and volcano plot results demonstrated that the IL36RN mutated gene was significantly down‐regulated, which was further validated by the GSE23586 dataset of periodontitis and healthy controls as per box plot." (PMID 34272761, 2021). "In the box plot, the IL36RN expressions were lowered in periodontitis patients compared to healthy controls significantly (p < 0.05)." (PMID 34272761, 2021). "Herein, the mild periodontitis showed significantly higher expression of IL36RN in PBMC and plasma compared to moderate and severe periodontitis (p < 0.05)." (PMID 34272761, 2021). "The present study has discovered and validated the down‐regulated expression of IL36RN in periodontitis and healthy controls with PBMC and plasma samples, similar to previous studies." (PMID 34272761, 2021). "Similarly, moderate periodontitis showed higher expression of IL36RN than severe periodontitis whereas lower expression than mild periodontitis patients (p < 0.05)." (PMID 34272761, 2021). "Furthermore, the clinical significance of IL36RN was evaluated in mild‐to‐severe patients of periodontitis by the receiver operating curve (ROC) using the area under the curve (AUC)." (PMID 34272761, 2021). "IL36RN can distinctively be detectable in periodontitis patients with PBMC and plasma, which can act as a down‐regulated mutated gene that might play an effective role in causing periodontitis." (PMID 34272761, 2021). "Besides, IL36RN expression and significance were observed in mild‐to‐severe periodontitis patients with PBMC and plasma samples." (PMID 34272761, 2021). "A total of 194 participants of public datasets, consisting of 97 cases of periodontitis and 97 cases of healthy control were retrospectively evaluated and explored the gene enrichment pathways and clinical significance of IL36RN expression accompanied by three different cytokines." (PMID 34272761, 2021). "IL36RN may involve by other inflammatory cytokines in the pathogenesis of periodontitis." (PMID 34272761, 2021). "Our study aims to find IL36RN in PBMC and plasma of the periodontitis patients and its clinical significance." (PMID 34272761, 2021). "Herein, IL36RN expressions were notably down‐regulated in PBMC and plasma of periodontitis patients compared to the healthy control group (p < 0.05)." (PMID 34272761, 2021). "A total of 194 participants were enrolled to evaluate IL36RN expression through PBMC and plasma samples of periodontitis (n = 97) and healthy controls (n = 97)." (PMID 34272761, 2021).
periodontitis (continued). "Thus, the diagnostic value of IL36RN can accurately distinguish between mild‐to‐severe or moderate‐to‐severe periodontitis patients with PBMC and plasma, and further may provide potential significance in diagnosing periodontitis." (PMID 34272761, 2021). "Our study discovered the IL36RN expression through GEO public databases and further validated by PBMC and plasma of periodontitis patients and healthy participants." (PMID 34272761, 2021). "While severe periodontitis represented the lowest expression of IL36RN among PBMC and plasma of mild and moderate periodontitis patients (p < 0.05)." (PMID 34272761, 2021). "IL36RN expressions were notably down‐regulated in PBMC and plasma of periodontitis patients." (PMID 34272761, 2021).
Psoriasiform dermatitis (2 papers, 2019 to 2025). A skin abnormality characterized by redness and irritation, with thick, red skin that displays flaky, silver-white patches (scales). "Mutations in the murine IL-36RN gene have been associated with a psoriasiform dermatitis phenotype, whereas mice deficient in IL-36 or IL-36R were protected from imiquimod-induced psoriasiform dermatitis." (PMID 31867327, 2019).
Autoimmunity (1 paper, 2025). The occurrence of an immune reaction against the organism's own cells or tissues. "This current study shows the genetic changes in genes related to autoimmunity such as pathogenic variants of IL36RN, RNASEH2B, and SLC29A3 genes." (PMID 39992598, 2025).
Crohn disease (1 paper, 2025). A gastrointestinal disorder characterized by chronic inflammation involving all layers of the intestinal wall, noncaseating granulomas affecting the intestinal wall and regional lymph nodes, and transmural fibrosis. "This study investigates the potential involvement of mutations in the IL-36 receptor antagonist (IL36RN, IL-36RA) in the pathogenesis of Crohn’s disease and evaluates the IL-36 signaling pathway as a drug target for IL36RN-mutated patients." (PMID 40447918, 2025). "We identified a heterozygous missense mutation in IL36RN (IL36RN S113L) in a therapy-refractory Crohn’s disease patient." (PMID 40447918, 2025). "Our findings indicate that pathogenic IL36RN mutations may contribute to the pathogenesis of Crohn’s disease in a subset of patients and that inhibiting IL-36 signaling could offer a personalized therapeutic approach for these patients." (PMID 40447918, 2025). "Our study indicates that IL36RN mutations contribute to the pathogenesis of Crohn’s disease in a subset of patients who may benefit from anti-IL-36R therapy." (PMID 40447918, 2025). "Finally, we identified three additional CD patients carrying missense IL36RN mutations in a cohort of 244 Crohn’s disease patients." (PMID 40447918, 2025). "We here identified four Crohn’s disease patients with heterozygous missense mutations in the IL-36 receptor antagonist (IL36RN, IL-36RA)." (PMID 40447918, 2025).
eczema (1 paper, 2021). "Specifically, this was the case for a TCIRG1 variant in a patient with pancytopenia, an IL36RN variant in a patient with refractory eczema, and in a UNC13D variant in a patient with hemophagocytic lymphiohistiocytosis." (PMID 34992599, 2021).
erythroderma (1 paper, 2024). "We present a patient with erythroderma with heterozygous mutations in IL36RN and CARD14, characterized by multiple lesions displaying what appeared to be normal‐looking spots." (PMID 39373130, 2024). "The patient had mutations IL36RN and CARD14, but it was unclear whether either mutation was associated with her erythroderma." (PMID 39373130, 2024). "However, no reports have shown an association between this IL36RN mutation and PRP‐like erythroderma." (PMID 39373130, 2024).
impetigo herpetiformis (1 paper, 2023). An impetigo that is characterized as a form of severe pustular psoriasis occurring in pregnancy. "Recently, the role of IL36RN variants was shown to underlie most cases of impetigo herpetiformis particularly in the East Asian populations." (PMID 38103162, 2023). "IL36RN mutations have also been detected in other pustular dermatoses, including acrodermatitis continua and impetigo herpetiformis." (PMID 38103162, 2023).
Insulin resistance (1 paper, 2022). Increased resistance towards insulin, that is, diminished effectiveness of insulin in reducing blood glucose levels. "Il36rn-knockout mice are protected to develop diet-induced weight gain and insulin resistance with these changes being associated with the higher abundance of A. muciniphila in their colon." (PMID 35222417, 2022).
keratinization disease (1 paper, 2021). "Loss-of-function mutations in IL36RN, which encodes IL-36Ra, cause a recessively inherited autoinflammatory keratinization disease known as deficiency of IL-36Ra (DITRA) (IL36RN [MIM: 605507]), because IL-36Ra’s role is to suppress excessive IL-36 signaling." (PMID 34944704, 2021).